PPARA (peroxisome proliferator activated receptor alpha)
Diseases named in the same sentence as PPARA in open-access papers (continued):
Sharing a sentence is not in itself a finding about the gene and the disease.
tumor (continued). "However, it should be kept in mindthat PPARα was first described to promote peroxisome proliferation andhepatocellular neoplasia in rodents which conversely to humans, and themajority of other species, turned out to be particularly sensitive to PPARligands." (PMID 18509489, 2008). "In this review, we focus on the contribution of PPARα to tumor and endothelial cell functions and provide compelling evidence that PPARα can be viewed as a new class of ligand activated tumor “suppressor” gene with antiangiogenic and antitumorigenic activities." (PMID 18725983, 2008). "Interestingly, PPARα deficient granulocytes carried TSP-1, a protein that inhibits angiogenesis, leukocyte migration and tumor growth." (PMID 17327920, 2007). "In PPARα KO mice that received the control antibody (IgG2b), tumor growth remained inhibited." (PMID 17327920, 2007). "Therefore, our finding suggests that PPARα regulates an aspect of inflammation that is different from that controlled by NF-κB and hence, PPARα modulation of inflammation affects tumor growth independently of NF-κB." (PMID 17327920, 2007). "In fact, TSP-1 was elevated in the plasma and tumor tissue of PPARα KO mice." (PMID 17327920, 2007). "This may be due in part to cell-autonomous effect of PPARα, because it is expressed in many tumor cell lines." (PMID 17327920, 2007). "Characterizing the effects from PPARα agonism in the identification of key events that may constitute a cogent MOA hypothesis for tumor induction has yet to be resolved." (PMID 16966103, 2006). "Anti-tumour effects of PPARα-specific agonists appear to be less commonly reported." (PMID 16569247, 2006). "In the last 10 years, there has been a considerable evolution in the hypotheses about the relationship between PPARα agonism and tumor induction in rodents." (PMID 16966103, 2006). "Peroxisome proliferator-activated receptors (PPARs), including PPARα, δ, and γ, are important regulators of glucose homeostasis, integrating environmental signals and metabolic pathways, and they also regulate the cell cycle to influence tumor progression 15-17." (PMID 40959276, 2025). "Therefore, PPARα may regulate tumor cell proliferation by interfering with the expression of SREBP1 and FAS." (PMID 37305395, 2023). "Since tumor cells grow rapidly and require adequate nutrients and oxygen supply, they enhance local blood perfusion by releasing angiogenic factors that would otherwise lead to hypoxia and death, a process significantly influenced by PPARα, which can inhibit angiogenesis to varying degrees." (PMID 37251321, 2023). "In addition, the cell cycle regulators p21 and p27, which are closely related to tumor suppression, may participate in the suppression of EMC in association with PPARα." (PMID 37305395, 2023). "However, from a metabolic point of view, PPARα activation could also be beneficial in reducing tumor growth." (PMID 35954274, 2022). "However, the same research group, as well as the great majority of other laboratories, could establish an anti-angiogenic effect of PPARα activation, implying different PPARα agonists in a variety of animal tumor models." (PMID 35954274, 2022). "Lastly, it is necessary to bear in mind that, in tumor tissues, PPARα could be affected by various ligands, including fatty acids and pollutants from the environment such as phthalates or pesticides, which could induce the expression of different target genes than in our in vitro study." (PMID 36101378, 2022).
tumor (continued). "Consequently, the tumor cells which adapt poorly to the PPARα-mediated anti-inflammatory response and enhanced fatty acid oxidation may become less proliferative and undergo apoptotic, necrotic, or autophagic cell death." (PMID 33946986, 2021). "Thus, PPARα activation in stromal endothelial cells inhibited the biosynthesis of pro-angiogenic factors while promoting the secretion of anti-angiogenic factors, thereby abrogating angiogenesis and limiting nutrient supply to attenuate tumor progression." (PMID 33946986, 2021). "Furthermore, restoring the expression of MARC2 could increase the expression of HLA-C and B2M via PPARA-related lipid metabolism signaling pathways, which could facilitate tumor antigen presentation to the tumor-infiltrating T cells." (PMID 35173763, 2021). "Moreover, according to the C1-C6 immune subtypes previously identified by investigators, we classified tumor samples by representative immune signatures and examined the RNA-seq level of PPARA, PPARD, PPARG, PPARGC1A, and PPARGC1B from C1 to C6, which were all seen to have differential expressions." (PMID 33029111, 2020). "Importantly, these findings suggest that targeting PPARα may reverse the immune dysfunctional state of DCs and therefore could be a therapeutic strategy to improve anti-tumor immunotherapy." (PMID 33086073, 2020). "In addition, we found that tumor growth in PPARα−/− mice was slower than in WT mice." (PMID 33086073, 2020). "Thus, we suggested that the mechanisms by which PPARα activation suppressed tumor progression might modulate energy metabolism through the downregulation of the Warburg effect." (PMID 31724941, 2019). "PFOS also significantly stimulates both PPARα and PPARγ, which could also modulate tumor growth." (PMID 27927180, 2016). "We also found that PPARα was down-regulated in human HCCs compared with adjacent non-tumor tissue (P < 0.0001) and was silenced or down-regulated in all 5 HCC cell lines, further implying that PPARα may regulate HCC progression with a potential tumor suppressive property." (PMID 25327562, 2014). "Thus, elucidating the role of PPARα whether acting as a tumor promoter or suppressor is important in understanding its contribution to liver carcinogenesis and may provide clues in developing effective treatments against this malignance." (PMID 25327562, 2014). "Thus, reduction of PPARα and PPARγ expression may be an additional mechanism for facilitating the proinflammatory and tumor-promoting effects of GW501516." (PMID 21318167, 2010). "Moreover, inhibition of the PPARA signaling pathway may also play an important role in tumor progression." (PMID 20507583, 2010). "Thus, in the skin, activation of PPARα inhibits tumor promotion." (PMID 21297902, 2010). "Thegeneration of PPARα null mice has provided an excellenttool not only to determine whether the effects exerted by PPARα ligand are indeed PPARα-dependent, but also for discerningbetween host versus tumor-mediated PPARα responses." (PMID 18725983, 2008). "This study clearly indicates that bothactivation of PPARα in specific host cells (i.e., endotheliacells) and concomitant inhibition of PPARα in immuno cells (i.e., granulocytes) mightlead to the same effects, namely protection from tumor growth." (PMID 18725983, 2008). "In the mouse model of skin carcinogenesis, an animal topicallytreated with PPARα ligands exhibited an approximately 30% lower skin tumoryield compared with mice treated with vehicle, thus indicating that the activationof PPARα may suppress the earliest stages of tumor development." (PMID 18645617, 2008). "However, tumor inhibition was even stronger in WT animals whose bone marrow had been replaced with that of PPARα KO mice as well as in PPARα deficient hosts, again suggesting that not only is PPARα necessary for tumor growth, but that its absence confers a tumor suppressor activity on neutrophils." (PMID 17327920, 2007). "Similarly, tumor metastasis was also suppressed in PPARα KO mice." (PMID 17327920, 2007).
tumor (continued). "However, it cannot be excluded that the suppressor activity carried by PPARα-deficient bone marrow cells overrides a potential tumor stimulatory contribution of PPARα in other, non-bone marrow derived host cells, such as from the local stroma." (PMID 17327920, 2007). "However, in the aged liver, a decrease in hepaticantioxidant activity, coupled with a PPARα agonist-induced increase inliver oxidative stress and antiapoptotic effect of PPARα agonists may expose theselivers to the point of tumor formation." (PMID 18317516, 2007). "Exosomes from prostate cancer cells further impair tumor-infiltrating CD8+ T cells by releasing IL-8, which activates PPARα in receptor cells and subsequently upregulates CPT1A expression in tumor cells, disrupting energy metabolism." (PMID 41219902, 2025). "PPARα depletion impaired cytokine production and antigen-presenting activity in ACE-expressing macrophages, resulting in reduced tumor antigen-specific CD8+ T-cell generation." (PMID 39910334, 2025). "Anwulignan exerts unique effects by modulating the PPARα/CXCR2 signaling pathway in the spinal dorsal horn, reducing the tumor burden and increasing osteoblast activity." (PMID 40079428, 2025). "Our findings suggest that Anwulignan mitigates BCP through a distinct synergistic mechanism, which involves the upregulation of PPARα expression to inhibit the expression of CXCR2, a reduction in tumor burden, and the promotion of osteoblast synthesis." (PMID 40079428, 2025). "By regulating the PPARA signaling pathway, FABP1 influences the uptake of long-chain fatty acids (LCFAs) by tumor cells, thereby altering the tumor microenvironment." (PMID 40717587, 2025). "PPARα depletion impaired cytokine production and antigen-presenting activity in ACE-overexpressing macrophages, resulting in reduced tumor antigen-specific CD8+ T cell activity." (PMID 38746124, 2024). "PPARα agonists, such as fenofibrate and bezafibrate, improve CD8+ T-cell functions and synergize with PD-1 blockade to inhibit tumor growth." (PMID 39402302, 2024). "Consistently, a significant decrease in the mRNA levels of PPARa, ACLY, FASN, ACSL1 and ACSL5 was observed in the livers of C26 tumor-bearing mice compared with control mice." (PMID 38245529, 2024). "In an ACT model, CD8+ T cells treated with the PPARα agonist fenofibrate improved CD8+ TIL function and synergized with PD-1 blockade to delay tumor growth." (PMID 39402302, 2024). "The “PPARα/RXRα activation” and “LXR/RXRα activation” canonical pathways were also predicted to be inhibited in Pparg-/-epi mouse skin and the tumor datasets." (PMID 39195246, 2024). "The role of PPARA in LINC01116‐mediated lipid metabolic reprogramming, tumor proliferation, migration, and invasion was also examined by overexpressing or knocking down PPARA." (PMID 38460179, 2024). "Activated PPARα further regulates glucose, lipid, and cholesterol metabolism of tumor cells, and inhibition of FAS in mice can lead to PPARα dysfunction." (PMID 37251321, 2023). "The study confirmed that CPT1C is a novel target gene of PPARα, and that knockout of PPARα leads to a decrease in CPT1C expression, which inhibits the proliferation of MDA-MB-1 and PANC-1 tumor cell lines in a CPT1C-dependent manner." (PMID 37251321, 2023). "PPAR-γ is one of the three different isoforms of the PPARs family (PPARα, PPARβ/δ and PPAR-γ) and acts as a tumor suppressor in CRC." (PMID 37762927, 2023). "Both PPARA and CNR2, potential target genes of β-elemene, have been shown to be involved in the tumour development process of NSCLC." (PMID 37980372, 2023). "Treatment with a PPARα agonist during OT-I cell in vitro stimulation increases the frequencies of GrmB+ and IFN-γ+ CD8+ TILs in vivo and markedly delays tumor progression." (PMID 37342333, 2023). "Since ARID1A is regarded as an important tumor suppressor in EMC, the effects of PPARα silencing and activation on the expression of ARID1A were examined." (PMID 37305395, 2023).
tumor (continued). "Like the knockdown of PPARA or SLC47A1, hematoxylin and eosin (H&E) staining observed that the combination of IKE and cimetidine resulted in increased necrotic-like changes in tumor tissue compared to the treatment group alone." (PMID 36575162, 2022). "Acyl-CoA oxidase 2 (ACOX2) has been proposed to inhibit tumor progression and the metastasis of HCC trough a PPARα-dependent pathway." (PMID 35954274, 2022). "While only the FOXM1, PYROXD1, hTERT and MCTP1 genes were overexpressed in CRC tumor tissues relative to the normal adjacent tissues at all the stages, but FOXM1, PYROXD1, hTERT, PIM3, BMI1, PPARA and MCTP1 were found to have stage-dependent expression." (PMID 35845311, 2022). "These actions are mediated through PPARα, the receptor targeted by PFAS, providing the potential for synergistic tumor promotion." (PMID 34836157, 2021). "Among them, EETs and 11-HETE were the most interesting, with EETs being a vital factor for tumour angiogenesis and 11-HETE being the only increased eicosanoid in all PPARα agonist-treated groups and tissues." (PMID 31791289, 2019). "Interestingly, the unique metabolic requirements of GSC compared to the aberrantly differentiated cells of the tumour mass 40 may explain the paradox of increased PPARA expression in mediating prolonged clinical survival 12 versus KD of PPARα in GSC inhibiting tumour growth." (PMID 30565681, 2019). "SCR and PPARα KD shRNA‐transduced G26 cells were stereotactically implanted in a NOD SCID murine model, and the effect on tumour initiation and progression was monitored." (PMID 30565681, 2019). "The vessel density in tumours, as determined by anti-CD31 staining, was significantly inhibited by PPARα activation, with the strongest inhibition being observed for Wyeth-14,643, followed by AVE8134 and then Bezafibrate." (PMID 31791289, 2019). "This study compared the effects of three different PPARα agonists on tumour progression and liver hepatomegaly and found that the novel PPARα ligand AVE8134 was an ideal choice for tumour treatment given its effectiveness and safety." (PMID 31791289, 2019). "We found that the PPARA and CREBBP expression value in HCC tissues was clearly down-regulated than in matched non-tumour tissues (P < 0.01)." (PMID 29780284, 2018). "This experimental evidence demonstrated the direct involvement of PPARα in GCs tumor resistance, since it is upregulated by DEX and is a well-known FAO regulator; in addition, PPARα antagonists revoked these effects and sensitized CLL cells to DEX." (PMID 29966227, 2018). "Therefore, PPARα could represent a novel therapeutic target for this rare chemoresistant tumor." (PMID 28594934, 2017). "Animal experiments provide promising results in field of PPARα-dependent regulation of CYP epoxygenases and consequent marked reduction of tumour mass volume and vascularization in mice." (PMID 27658584, 2016). "Peroxisome proliferator activated receptor alpha (PPARα) is a nuclear hormone receptor family transcription factor, which is involved in regulation of DME and tumor progression." (PMID 27834829, 2016). "We examined the mRNA expression of PPARα in 27 paired tumor and adjacent normal primary HCC samples and found that PPARα was markedly down-regulated in tumor tissue compared with adjacent normal tissue (P < 0.001)." (PMID 25327562, 2014). "PPARγ ligands are also potent angiogenic inhibitors and PPARα agonists suppress VEGF production, endothelialcell proliferation, and tumor growth in mice." (PMID 18551186, 2008). "This review summarizes the current understanding of the role of PPARα and its ligands in the regulation of COX-2 and VEGF gene expression in the context of tumor progression." (PMID 18670614, 2008). "In contrast, in PPARα KO mice where TSP-1 is constitutively high, it would act as an inhibitor of tumor growth, perhaps through its antiangiogenic effects." (PMID 17327920, 2007).
tumor (continued). "Genetically depleting PPARα in mice, pharmacologically inhibiting C24:4 (n-6)-induced PPARα in the nucleus or directly suppressing PPARα activity effectively attenuates PLA2G16-C24:4 (n-6) axis-based immune dysfunction of CD8+ T cells and their according anti-tumor activities." (PMID 41241920, 2025). "Consistent with fibrate-mediated PPARα activation reducing IL-6 in vivo, we show that PPARα depletion or miR-BART20-3p overexpression both elevate IL-6 in GC cells, linking viral miRNA activity to inflammation-driven tumor progression." (PMID 40732023, 2025). "Mechanistically, we determined that PPARα is the critical molecule governing the metabolic switch upon Linc01056 knockdown in HCC cells and indeed, PPARα inhibition restored the sorafenib response in HCC cells in vitro and HCC tumours in vivo." (PMID 38582885, 2024). "Several PPARα antagonists, including NXT629, AA452, MK886, and IB66, also suppress tumor growth." (PMID 39519311, 2024). "A separate study is ongoing in HCC, a tumor type not adequately represented in this phase I study, but of particular interest due to the high expression of PPARα." (PMID 38551394, 2024). "Recently, a Phase I interventional clinical trial (ClinicalTrials.gov ID NCT03829436) is ongoing to explore the tolerability, safety and tumor inhibiting activity of TPST-1120, selective antagonist of PPARα as monotherapy and with nivolumab, an anti-PD1 antibody against solid tumors including CRC." (PMID 38372868, 2024). "PPARα antagonists such as NXT629, AA452, MK886, and GW6471 suppress tumor growth." (PMID 39519311, 2024). "These controls indicate that it is the lack of PPARα in the A10-PPARα-Cre mice that is affecting the anti-tumor response." (PMID 38746124, 2024). "To determine whether PPARα is involved in tumorigenesis, we investigated the effects of treatment with GW6471 on the in vivo tumor growth of A2780-SP cells." (PMID 39519311, 2024). "A PPARA antagonist, NXT629, demonstrated the capability of reducing tumor burden in a mouse model of CLL, suggesting that PPARA may have a tumor-suppressive role in CLL." (PMID 37404899, 2023). "Similar results were obtained from mice with melanoma exposed to hypoglycemia and hypoxia, which up-regulated PPARα-dependent fatty acid oxidation, a metabolic switch that preserved intra-tumoral CD8+ Teff functions and attenuated tumor progression in conjunction with PD1 blockade." (PMID 37686465, 2023). "NR2C2, MAPK8, PPARA, and PTGS2 are all downregulated in tumor versus normal tissues." (PMID 35814450, 2022). "Our result showed that the RNA pattern of PPARA was not considerably altered in tumor and normal parallel tissues (P ≤0.05)." (PMID 35845311, 2022). "Combined regulatory activity, not necessarily monoactivity in tumor tissues is required, as exemplified for mTOR inhibitors, α-interferon, chemotherapy, PPARα/γ agonists." (PMID 35814409, 2022). "In summary, while PPARA, VDR, SLC16A1 and PAPSS2 supply the building blocks to synthesize macromolecules, GPX1 provides redox defense to counteract oxidative stress produced as a consequence of the high proliferation rates of tumor cells." (PMID 35565211, 2022). "In addition, miR-580-5p can be combined with PPARA in HCC cells to stimulate the production and secretion of C-C chemokine ligand 2 (CCL2) and modify the tumor microenvironment." (PMID 35264957, 2022). "The knockdown (KD) of PPARα reduced the proliferative and tumor-forming capacities of GSCs, and xenografts failed to establish viable intracranial tumors." (PMID 35954274, 2022). "Moreover, PPARα agonists can further promote fatty acid catabolism and improve the ability of CD8+ T cells to arrest tumor progression." (PMID 35392570, 2022). "The PPARA expression pattern between tumor and normal adjacent tissues was not considerably different P (H) = (0.7)." (PMID 35845311, 2022). "Yet, unlike PPARα and PPARγ, PPARβ/δ, which is ubiquitously expressed in almost all tissues, displays an apparent pro-tumor activity." (PMID 33946986, 2021).